PLAA (phospholipase A2 activating protein)
Description:
Plays a role in protein ubiquitination, sorting and degradation through its association with VCP. Involved in ubiquitin-mediated membrane proteins trafficking to late endosomes in an ESCRT-dependent manner, and hence plays a role in synaptic vesicle recycling (By similarity). May play a role in macroautophagy, regulating for instance the clearance of damaged lysosomes. Plays a role in cerebellar Purkinje cell development (By similarity). Positively regulates cytosolic and calcium-independent phospholipase A2 activities in a tumor necrosis factor alpha (TNF)- or lipopolysaccharide (LPS)-dependent manner, and hence prostaglandin E2 biosynthesis.
Synonyms: PLA2P; PLAP; FLJ11281; FLJ12699; DOA1; NDMSBA
Tractability: Small molecule: a high-quality ligand is known; it belongs to a druggable protein family. Antibody: the Human Protein Atlas places it where antibodies can reach. PROTAC: ubiquitination databases record sites on it; its protein half-life has been measured; a small molecule that binds it is known.
Gene: Protein-coding gene on chromosome 9 (26,903,372 to 26,947,490, reverse strand). Ensembl gene ENSG00000137055.
Subcellular location: Nucleus; Cytoplasm; Synapse
Subcellular location (Human Protein Atlas): Cytosol; Plasma membrane; Nucleoplasm
Gene Ontology:
Molecular function: phospholipase A2 activator activity; protein binding; ubiquitin binding
Biological process: cellular response to lipopolysaccharide; macroautophagy; negative regulation of protein K63-linked ubiquitination; phospholipid metabolic process; positive regulation of dendrite extension; positive regulation of neuron migration; positive regulation of prostaglandin biosynthetic process; positive regulation of synaptic vesicle recycling; proteasome-mediated ubiquitin-dependent protein catabolic process; protein unfolding; signal transduction; ubiquitin recycling; ubiquitin-dependent protein catabolic process via the multivesicular body sorting pathway
Cellular component: ATPase complex; cytoplasm; cytosol; extracellular exosome; nucleoplasm; nucleus; plasma membrane; synapse; cytoplasmic ubiquitin ligase complex
Genetic constraint (gnomAD): Loss-of-function variants: 26 observed, 53.2 expected, observed/expected ratio (o/e) 0.49, 90% interval 0.36 to 0.68. The upper end of that interval is the gene's LOEUF score, 0.68, which puts it in group 2 of 6, group 1 being the genes least tolerant of losing a copy. Missense variants: 686 observed, 737.35 expected, observed/expected ratio (o/e) 0.93, 90% interval 0.87 to 0.99. Synonymous variants: 307 observed, 268.72 expected, observed/expected ratio (o/e) 1.14, 90% interval 1.04 to 1.26.
Homologues: Orthologues: chimpanzee PLAA (99% identical), macaque PLAA (99% identical), dog PLAA (96% identical), rabbit PLAA (96% identical), rat Plaa (94% identical), mouse Plaa (94% identical), pig PLAA (94% identical), guinea pig PLAA (89% identical), tropical clawed frog plaa (75% identical), zebrafish plaa (66% identical), Drosophila melanogaster Plap (37% identical), Caenorhabditis elegans ufd-3 (29% identical).
Diseases named in the same sentence as PLAA in open-access papers:
PLAA is named in the same sentence as 34 diseases in open-access papers, as found by Europe PMC text mining. Sharing a sentence is not in itself a finding about the gene and the disease. The quoted sentences say what the papers report.
ovarian carcinoma (4 papers, 2022 to 2025). A malignant neoplasm originating from the surface ovarian epithelium. "In ovarian cancer and other malignancies, low expression of phospholipase A2 activating protein (PLAA) is linked to a poor prognosis." (PMID 40919129, 2025). "Our findings demonstrate a suppressive role, as well as underlying mechanism, of PLAA in ovarian cancer metastasis, which may provide a potential approach to block ovarian cancer metastasis in clinic." (PMID 35869392, 2022). "Meanwhile, PLAA inhibited metastasis of ovarian cancer by inhibiting transient receptor potential channel canonical 3 (TRPC3)-mediated the intracellular Ca2+ level." (PMID 35869392, 2022). "Our results together suggest that PLAA inhibits ovarian cancer metastasis in a TRPC3 dependent manner." (PMID 35869392, 2022). "PLAA inhibited the migration and invasion of ovarian cancer cells and metastasis of transplanted tumor in the orthotopic xenograft mouse model." (PMID 35869392, 2022). "In the present study, we found that PLAA expression was significantly downregulated in ovarian cancer tissues, and patients with lower PLAA expression presented poorer prognosis." (PMID 35869392, 2022). "Here, we found that PLAA was significantly downregulated in ovarian cancer highly metastatic cell lines and patients, and the low expression of PLAA was associated with poorer prognosis and high-risk clinicopathological features of patients." (PMID 35869392, 2022). "The results showed that PLAA were lower in highly metastatic cell lines than those in parental cell lines, and were lower in ovarian cancer cells than those in normal ovarian cells." (PMID 35869392, 2022). "We utilized RNA-seq to identify candidates of PLAA downstream targets, and found TRPC3 to be upregulated in ovarian cancer cells with PLAA knockdown and there was a reverse correlation between PLAA and TRPC3 expression in ovarian cancer cells and tissues." (PMID 35869392, 2022). "The endogenous expression of PLAA in ovarian cancer cell lines with different metastatic abilities, including A2780-M, A2780, HO8910PM, HO8910, and the normal ovarian epithelial cell line IOSE-80 were validated by western blot and RT-qPCR." (PMID 35869392, 2022). "Our results collectively demonstrate that PLAA inhibits ovarian cancer metastasis via downregulating TRPC3-mediated intracellular calcium level." (PMID 35869392, 2022). "Functionally, PLAA suppressed migration and invasion of ovarian cancer cells and metastasis in the orthotopic xenograft mouse model." (PMID 35869392, 2022). "In this study, we observed that PLAA expression was significantly downregulated in two highly metastatic ovarian cancer cells than that in lower metastatic cells, and in ovarian cancer tissues compared to ovarian benign tumor tissues." (PMID 35869392, 2022). "We thus profiled a pair of epithelial ovarian cancer cell lines with different metastatic potentials by using proteomics, and discovered that phospholipase A2-activating protein (PLAA) was downregulated in highly metastatic ovarian cancer cells." (PMID 35869392, 2022). "Our results together demonstrate that PLAA acts as a tumor metastatic suppressor in ovarian cancer." (PMID 35869392, 2022). "In addition, PLAA protein expression were detected to be significantly lower in ovarian cancer tissues than that in benign tumor tissues." (PMID 35869392, 2022). "Our data together suggest that patients with lower PLAA expression present shorter survival and PLAA may be a potential biomarker for predicting ovarian cancer prognosis." (PMID 35869392, 2022). "Interestingly, PLAA protein and mRNA expression was further decreased in metastatic ovarian cancer as compared with the primary ovarian cancer they were derived from." (PMID 35869392, 2022).
ovarian carcinoma (continued). "All our findings suggest that PLAA acts as a tumor suppressor in ovarian cancer metastasis, and PLAA may have a potential to be clinically used as a biomarker associated with patient prognosis and a therapeutic target in metastatic ovarian cancer." (PMID 35869392, 2022). "We additionally collected 56 fresh tissue samples of ovarian cancer and 12 fresh tissue samples of ovarian benign tumor for PLAA mRNA detection, and found PLAA mRNA was significantly lower in cancer tissues, especially reduced in patients with advanced stage than the early stage." (PMID 35869392, 2022). "In addition, PLAA expression was decreased in metastatic ovarian cancer tissues as compared with the primary ovarian cancer tissues that they were derived from." (PMID 35869392, 2022). "Our study verified the function and mechanism of the PLAA-METTL3-TRPC3 axis involved in ovarian cancer metastasis, with a view to providing a potential therapeutic approach for ovarian cancer." (PMID 35869392, 2022). "In another study, phospholipase A2 activating protein (PLAA) degraded METTL3 via the ubiquitination pathway, which resulted in the destabilization of the m6A-modified mRNA oncogene TRPC3 and prevented the metastasis of ovarian cancer cells." (PMID 37194218, 2023). "Mechanistically, PLAA inhibited METTL3 expression through the ubiquitin-mediated degradation and destabilized TRPC3 expression via METTL3-mediated m6A modification, which consequently suppressed intracellular calcium concentration and ovarian cancer metastasis." (PMID 35869392, 2022).
microcephaly (3 papers, 2023 to 2025). A congenital or acquired developmental disorder in which the circumference of the head is smaller than normal for the person's age and sex. "Individuals with PLAA mutations typically present with progressive microcephaly, profound GDD, and severe spastic quadriparesis, often accompanied by dystonia." (PMID 40243517, 2025). "Mutations in the PLAA gene cause neurodevelopmental disorder with progressive microcephaly, spasticity, and brain anomalies (NDMSBA; OMIM #617527), a rare autosomal recessive condition." (PMID 40243517, 2025). "To date, only biallelic mutations in PLAA gene have been implicated in a Mendelian disease characterized by an early lethal infantile epileptic encephalopathy associated with progressive microcephaly, spasticity, and brain anomalies (NDMSBA) [MIM:617527]." (PMID 38650658, 2024). "This expands both the phenotypic and allelic heterogeneity associated with PLAA-related neurological disorders as the gene has only been implicated so far in ultra-rare autosomal recessive neurodegenerative disorders associated to microcephaly, leukodystrophy and early lethality." (PMID 38650658, 2024).
breast carcinoma (2 papers, 2022 to 2024). "Previous studies showed that PLAA was inactived in some cancers, including ovarian, lung, and breast cancer, and the application of PLAA polypeptide led to tumor regression in animal models of lung and breast cancer." (PMID 35869392, 2022).
developmental delay (2 papers, 2017 to 2024). "Here we describe, in four families, a severe early-onset neurodysfunction syndrome characterized by profound developmental delay and seizures resulting from homozygous mutations in the gene encoding ubiquitin binding protein Phospholipase A2 Activating Protein (PLAA [MIM: 603873])." (PMID 28413018, 2017).
Intellectual disability (2 papers, 2024). "Using exome or genome sequencing we identified PLAA de-novo missense variants, affecting conserved residues within the PUL domain, in children affected with neurodevelopmental disorders (NDDs), including psychomotor regression, intellectual disability (ID) and autism spectrum disorders (ASDs)." (PMID 38650658, 2024).
Tremor (2 papers, 2017 to 2024). An unintentional, oscillating to-and-fro muscle movement about a joint axis. "In neurons, reducing PLAA function disrupts synaptic structure and synaptic vesicle recycling, resulting in impaired synaptic function, as demonstrated by electrophysiology and gross phenotypes (tremor, ataxia, neuromuscular weakness)." (PMID 28413018, 2017).
dry eye (1 paper, 2015). "Different proteins involved with dry eye dysfunction: ANXA1, ANXA11, CST4, PRDX5, PLAA and S100A6; were validated as biomarkers." (PMID 26287192, 2015).
Leukoencephalopathy (1 paper, 2017). This term describes abnormality of the white matter of the cerebrum resulting from damage to the myelin sheaths of nerve cells. "published a missense c.2254C>T mutation in human PLAA resulting in a non-destabilizing p.Leu752Phe change in the PUL domain, causing a similar but milder clinical phenotype, which they diagnosed as leukoencephalopathy." (PMID 28413018, 2017).
lymph node metastasis (1 paper, 2022). "Importantly, we found that patients with lower PLAA expression were associated with high-risk clinicopathological features, such as FIGO stage, lymph node metastasis and CA125 level, and presented shorter survival." (PMID 35869392, 2022).
Stroke (1 paper, 2019). Sudden impairment of blood flow to a part of the brain due to occlusion or rupture of an artery to the brain. "Three of these loci are linked to genes with experimental evidence of influence on outcome from animal models of stroke.19, –, 21 First, the intronic variant in PLAA (rs13299556) was both one of the top findings in the ordinal analysis and associated with the dichotomized outcome at a low p value." (PMID 30796134, 2019).
infection (3 papers, 2018 to 2021). The state of being infected such as from the introduction of a foreign agent such as serum, vaccine, antigenic substance or organism. "The fact that at least ProA, PlaA and LapA have a role in intracellular infection by L. pneumophila also further implies an importance for T2SS in the intracellular parasitism and ecology of Aquicella." (PMID 31166887, 2019). "The finding that ProA processes LapA and LapB adds to past work showing that ProA cleaves PlaA and PlaC and is required for strain 130b infection of V. vermiformis and N. lovaniensis." (PMID 29666285, 2018).
tumor (3 papers, 2021 to 2022). "Phospholipase A2-activating protein has been relatively intensively studied in humans and is involved in apoptosis and tumor regression; however, there is only a single study related to its functional characterization in fungi." (PMID 35154058, 2022).
cancer (2 papers, 2021 to 2022). A tumor composed of atypical neoplastic, often pleomorphic cells that invade other tissues. "Previous studies revealed that PLAA inactivity was associated with ovarian and other cancers." (PMID 35869392, 2022). "It has been found that phospholipase A2-activating protein (PLAA) is inactivated in some cancers, but its role in cancer metastasis remains unknown." (PMID 35869392, 2022). "However, the role of PLAA in cancer metastasis is poorly known to date." (PMID 35869392, 2022). "We further found a significant negative correlation of the expression between PLAA and TRPC3 mRNA in 56 cancer samples, and IHC staining assay also showed the negative correlation between PLAA and TRPC3." (PMID 35869392, 2022).
neurological disease (2 papers, 2017 to 2024). "The identification of abnormal Plaa-p97 interaction as a possible disease mechanism implicates the downstream vesicle recycling in the pathogenesis of dominant PLAA-related neurological disorders due to de novo mutations affecting the PUL domain." (PMID 38650658, 2024). "Our study highlights the phenotypic and allelic heterogeneity underlying PLAA-related neurological disorders." (PMID 38650658, 2024). "Together, these data support use of the unifying term PLAA-associated neurodevelopmental disorder (PLAAND), which covers the phenotypic spectrum of human neurological disease resulting from different PLAA mutations." (PMID 28413018, 2017).
PLAA also shares sentences with these, for which no sentence is quoted: neurodevelopmental disorder (5 papers); Ataxia (1); autism spectrum disorder (1); benign tumor (1); cerebral palsy (1); cervical cancer (1); Coffin-Siris syndrome (1); Dystonia (1); Epileptic encephalopathy (1); Hydrocephalus (1); Hypsarrhythmia (1); infantile epileptic encephalopathy (1); language delay (1); lymphedema (1); Motor delay (1); optic atrophy (1); ovarian benign tumor (1); Progressive encephalopathy (1); rheumatoid arthritis (1); Seizure (1).